ALB (albumin)
Diseases named in the same sentence as ALB in open-access papers (continued):
Sharing a sentence is not in itself a finding about the gene and the disease.
malnutrition (continued). "In summary, BChE and albumin levels should be interpreted in the context of systemic inflammation and malnutrition, both conditions that are hallmarks of malignant disease." (PMID 29113384, 2017). "This high rate of malnutrition was consistent with the laboratory work-up, where 76.2% (n = 231) had albumin levels below normal and 37.0% (n = 121) had low pre-albumin levels." (PMID 31011021, 2017). "Transthyretin and albumin were used as biochemical markers of malnutrition to evaluate the prevalence and to categorize control group and study group into moderate, severe, and normal." (PMID 28932602, 2017). "Serum albumin is a common tool used to measure nutritional status and can help categorize the level of malnutrition." (PMID 29027963, 2017). "Protein markers, such as albumin and prealbumin (i.e., transthyretin), were once the standard blood biomarkers for diagnosing malnutrition during hospital admissions." (PMID 28771192, 2017). "A further aim was to determine the criterion validity with respect to biochemical markers of malnutrition such as serum albumin, transferrin, cholesterol and lymphocytes, the body mass index and the mini nutritional assessment." (PMID 27708835, 2016). "Some laboratory parameters related to malnutrition were improved, with significant increases in albumin and hemoglobin after intervention." (PMID 27005661, 2016). "In advanced cancer patients, the levels of serum albumin fall sharply because malnutrition and systematic inflammatory response to tumors both suppress albumin synthesis." (PMID 27349744, 2016). "Since there are a multitude of disease processes that alter the level of albumin, it becomes an unreliable serum marker for malnutrition." (PMID 27174435, 2016). "TIBC was superior to albumin and CRP as a malnutrition-inflammation associated serum biomarker and predictor of physical function in this low-comorbidity patient sample." (PMID 26982967, 2016). "Individuals with conditions such as malnutrition, chronic inflammation, enteropathy, or liver disease can have reduced serum albumin concentrations." (PMID 27405321, 2016). "Older people are generally more likely to develop malnutrition as they age, so our finding that albumin level correlated with patient age in AD was reasonable." (PMID 27336725, 2016). "One study found that using serum albumin levels < 3.5 g/dL as the sole parameter for malnutrition would have low specificity for identifying nutritional status in the functionally impaired elderly." (PMID 27174435, 2016). "Diminished levels of total protein or albumin, which are indicators of malnutrition, can prevent a proper immune response." (PMID 27258377, 2016). "Nevertheless, the advantage from increments of albumin will be limited if there is excessive malnutrition at the beginning." (PMID 27015223, 2016). "These pathophysiological alterations in HF not only lead patients to a metabolically demanding condition but also to a malnutrition status such as reduced ALB level in our studied patients (33.8 ± 4.7 mg/L)." (PMID 27428188, 2016). "Serum albumin is a recognised marker of malnutrition in dialysis patients, and in turn, malnutrition a known predictor of poor outcome in PD." (PMID 27300372, 2016). "In dialysis patients we tested parameters possibly related to the 6-minute walk test result due to their clinical significance as markers of comorbidity, anemia, malnutrition and inflammation: Davies comorbidity grade, hemoglobin, albumin, CRP and TIBC." (PMID 26982967, 2016). "Low serum albumin level, low body mass index, and hypocholesterolemia have been regarded as malnutrition status." (PMID 27608939, 2016). "If we had considered hypoalbuminemia as a sign of malnutrition, then the prevalence of malnutrition in our sample would have risen from 33.3% to 100% since all the patients in our sample had albumin levels below the reference value." (PMID 27982165, 2016).
malnutrition (continued). "Of the 28 patients who were diagnosed with malnutrition based on total protein, serum albumin, or hemoglobin level, all but one family caregiver (96.4%) answered that the patient had neither loss of appetite nor weight loss." (PMID 27336725, 2016). "Even those patients that had other risk factors, the commonest denominator to this disease in Northern Uganda was malnutrition which was shown by low serum albumin level (<38 g/L), low BMI (<18.5) and with overt clinical features of malnutrition." (PMID 26052503, 2015). "Recipients were assessed based on serum albumin, cholesterol, or body mass index for the malnutrition factor and C-reactive protein level for the inflammation factor." (PMID 26194096, 2015). "On the other hand, malnutrition and systematic inflammation have been shown to suppress albumin synthesis, even leading to hypoalbuminemia (<35 g/L)." (PMID 26681341, 2015). "In the present study, AGR was calculated as AGR = albumin/(total protein—albumin), and it reflected both malnutrition and systemic inflammation in UTUC patients." (PMID 26681341, 2015). "The diagnosis of the nutritional status through the objective and subjective methodsshowed that the prevalence of malnutrition was 40.6% (n=28) through albumin, 73.9%(n=51) through the TLC, 49.2% (n=34) through the SGA, and only 7.2% (n=05) through theBMI." (PMID 26537145, 2015). "In ATARAO and ANRS, malnutrition was common across all indicators (BMI, hemoglobin, albumin) and persisted despite treatment." (PMID 26825478, 2015). "Malnutrition, which is reflected by reduced albumin, weakened several human immune defense mechanisms, which decreased the response to treatment in cancer patients." (PMID 26681341, 2015). "Decreased value of albumin concentration with the progressive age are mostly due to liver cirrhosis that alters liver function or malnutrition in geriatric dogs." (PMID 27047084, 2015). "Several markers, such as high sensitivity C-reactive protein (hs-CRP), interleukin (IL)-6, IL-8, and serum albumin levels (S[Alb]), were frequently applied to evaluate malnutrition, inflammation and atherosclerosis (MIA) syndrome in chronic dialysis patients." (PMID 25793462, 2015). "There have been previous reports of excess mortality in ESRD patients being attributed to low serum albumin levels, potentially a proxy for malnutrition, which are independent predictors of morbidity and mortality in this patient population." (PMID 26645204, 2015). "Conversely, the amount of plasma albumin is decreased in the elderly and in those having pathological conditions such as malnutrition, liver disease, renal disease, burns, and surgery." (PMID 25648333, 2015). "Albumin, which is produced by liver, is usually regarded as an index of malnutrition and cachexia when decreased." (PMID 26656866, 2015). "Analytical parameters such as albumin, prealbumin, transferrin, total lymphocyte, total cholesterol, creatinine and proteins help to identify malnutrition and liver dysfunction." (PMID 25608608, 2015). "As the nutritional status classified by both MNA-SF and NRS2002 deteriorated, BMI, serum albumin, hemoglobin, handgrip strength, mid-arm circumference and calf circumference of patients with malnutrition were lower (P < 0.05)." (PMID 26170020, 2015). "Based on serum albumin and triceps skin fold thickness, we have observed a high rate (77.8 %) of malnutrition." (PMID 26471898, 2015). "Serum-albumin levels respond slowly to malnutrition because this protein has a relatively long half-life in the organism (14–20 days) and a large reservoir (4–5 g/kg of body weight), making it a poor indicator of early protein depletion." (PMID 25254370, 2014). "Following adjustment for potential variables, BCLs were negatively correlated with serum albumin levels and malnutrition in these patients." (PMID 24428882, 2014).
malnutrition (continued). "Interestingly, a previous report demonstrated that lower serum albumin concentrations could have been caused by ongoing inflammation, poor health status, and malnutrition; these factors have also been shown to be associated with low muscle mass or accelerated muscle loss." (PMID 24723739, 2014). "Complement components are produced by the liver, and their levels correlated with albumin levels, the production of which is also impaired in malnutrition." (PMID 25153531, 2014). "The efficiency of the low-protein diet during the fetal period in inducing the malnutrition was confirmed by the reduced values in body weight, serum glucose, total protein and albumin, corroborating previous studies using the same diet." (PMID 25400700, 2014). "Compared with the Nutritional Risk Index (serum albumin and recent weight loss), BMI and serum albumin, SGA acted as a good predictor for malnutrition and complications." (PMID 23251271, 2013). "Albumin is a serum protein that can be used as an additional indicator of overall nutritional status and malnutrition." (PMID 24160554, 2013). "Although some markers e.g. body weight, serum albumin, etc are effective in identifying the patients with high risks of malnutrition, they have some limitations and can be influenced by other non-nutritional factors." (PMID 24349471, 2013). "Overall nutritional status, determined by level of serum albumin, was within the normal range for 99% of the participants (4.3 ± 0.4 g/dL); malnutrition (serum albumin <3.5 g/dL) was observed in only 1% of the group." (PMID 25089225, 2013). "The data showed that BMI, FM, and serum albumin decreased significantly in malnutrition group (BMI, P = 0.013; FM, P = 0.039; albumin, P = 0.037), while CRP and MIS significantly increased (CRP, P = 0.008; MIS, P = 0.000)." (PMID 24349471, 2013). "Low albumin is a reverse prognostic marker of survival in dialysis and post-transplant patients and is also often used as an indicator of malnutrition." (PMID 28197445, 2013). "In this study, as in other reports, malnutrition, inactivity, old age, low s-albumin and s-ALAT values, and high homocysteine values were associated with B6 deficiency and seem reasonable to have in mind." (PMID 23394203, 2013). "For the first time in hemodialysis patients to our knowledge, we demonstrated that malnutrition (a high MQSGA score and a low level of serum albumin) was closely associated with arterial calcification and the expressions of BMP2 and MGP." (PMID 23506394, 2013). "Malnutrition in animals is often characterised by low serum albumin and total protein concentrations and high levels of liver lipids." (PMID 22448911, 2012). "Serum albumin, which is routinely measured in developed countries and available in most inpatient and many ambulatory settings in Africa, is the most used laboratory parameter for nutritional assessment with low serum albumin indicating malnutrition." (PMID 22532840, 2012). "The scale is based on the evaluation of 4 parameters: 2 markers of malnutrition: albumin and prealbumin, and 2 markers of inflammatory state: CRP and α1acid glycoprotein (AAG)." (PMID 22574625, 2012). "According to the laboratory criteria of protein reserves, the results showed that 58.34% of the patients had mild malnutrition, consisting of plasma albumin between 3.0 and 3.9 g/dl." (PMID 23338736, 2012). "The objectives of this study are to address if and how albumin can be used as an indication of malnutrition in HIV infected and uninfected Africans." (PMID 22532840, 2012). "Serum albumin is greatly influenced by variable factors such as malnutrition, hydration status, and inflammation." (PMID 23245677, 2012). "Indicators of malnutrition include serum levels of albumin, prealbumin, and transferrin; total lymphocyte count; body weight and body mass index; triceps skinfold thickness; midarm muscle circumference." (PMID 22254136, 2011).
malnutrition (continued). "Independent variables examined in reported studies, which are essential in promoting the spontaneous closure of ECF, include control of malnutrition, hydroelectrolytic imbalance, serum albumin and elimination of sepsis." (PMID 21418588, 2011). "A mean BMI of 24.75 ± 3.82, along with the low total proteins, albumin, and A/G ratio, suggest malnutrition." (PMID 21943151, 2011). "All patients had a reduced albumin, most probably secondary to malnutrition and possibly malabsorption due to bowel disease." (PMID 20363170, 2010). "Of all, 25.9% had albumin less than 3.5 g/dl who were suffering from malnutrition or were exposed to it, and 27.5% had CRP more than 1 mg/dL which is indicative of the existence of inflammation in these people." (PMID 21526100, 2010). "Goldstein and co-workers and Orellana and colleagues found that serum albumin was a poor marker of nutritional status in children with severe malnutrition that were receiving HD and who were being given intradialytic parenteral nutrition (IDPN)." (PMID 18293013, 2009). "Low serum albumin indicates malnutrition; in our study, we made it clear that there is a strong relationship between serum albumin and anastomotic leak." (PMID 19881165, 2009). "Their study showed that the old-old elderly patients were more functional-dependent before fracture, had more comorbid diseases and had malnutrition as shown by low hemoglobin and serum albumin levels, and their functional outcome was poor." (PMID 19823651, 2008). "A biochemical assessment of nutritional status using plasma albumin level cut off point of <3.5 g/dl (507 μmol/l) as indicator of malnutrition showed that 53.9% of pre-HAART and 74.1% of HAART patients had lower albumin level." (PMID 16859567, 2006). "Malnutrition was defined by serum albumin or prealbumin levels, by a body weight ≤ 95% of ideal or a score ≤ 100 on the Nutrition Risk Index." (PMID 16952310, 2006). "However, after adjusting for nutritional status and nutritional markers, a higher mortality risk is observed in obese patients (OR 1.58; 95% CI 1.21–2.07 for malnutrition and OR 2.67; 95% CI 2.06–3.44 for serum albumin < 3.4 g/dL)." (PMID 41515273, 2026). "The markedly higher mortality at up to 10 years observed in the low-albumin group may therefore reflect a combination of malnutrition, persistent inflammation, and impaired host defense." (PMID 41517580, 2026). "Malnutrition, HIV positivity, chronic viral hepatitis, low albumin, and chronic alcoholics have a higher risk of hepatotoxicity and may benefit more from sequential regimen with or without pyrazinamide." (PMID 41561618, 2026). "Additionally, low serum albumin indicates malnutrition and serves as a marker of a weakened immune system in cancer sufferers." (PMID 41522516, 2026). "Notably, patients who were free from both sarcopenia and malnutrition demonstrated significantly higher serum albumin levels and creatinine levels." (PMID 41323996, 2025). "A decline in ALB levels reflects malnutrition and systemic inflammation, both of which may accelerate metabolic disturbances and exacerbate the deterioration of cardiac and renal function." (PMID 40740647, 2025). "Specifically, lower ALB values contributed markedly to positive model outputs (i.e., classification as active Mtb), consistent with the well-established role of hypoalbuminemia as a biomarker of systemic inflammation, malnutrition, and disease severity in TB." (PMID 41488479, 2025). "On the other hand, myocardial injury could be related to other malnutrition abnormalities, such as anemia, low albumin, lipid abnormalities, etc., that play a vital role as independent cardiometabolic risk factors." (PMID 40310053, 2025). "Relying solely on serum albumin for nutritional assessment may lead to misclassification, and underestimating malnutrition in certain patient populations." (PMID 40161084, 2025).
malnutrition (continued). "Moreover, chronic hypoperfusion, congestion,and inflammatory responses in heart failure patients can impair liver and kidneyfunction, leading to reduced albumin production and exacerbating malnutrition." (PMID 39867177, 2025). "In summary, the potential biological mechanisms behind the association between RDW, albumin, and COPD mortality may involve shorter telomere lengths, inflammation, oxidative stress, malnutrition, and hypoxemia." (PMID 40168268, 2025). "Decreased ALB should alert physicians to possible malnutrition and subsequent lower VD levels." (PMID 40313432, 2025). "In clinical practice, serum albumin is frequently used to identify malnutrition." (PMID 40648869, 2025). "Baseline BMI alone did not predict mortality; however, the addition of serum albumin level to define baseline nutritional risk led to better sensitivity in detecting baseline malnutrition and predicting 100‐day survival." (PMID 39866921, 2025). "We hypothesized that such a pro-inflammatory, poorly nourished state would also adversely affect bone health—inflammation can stimulate osteoclast activity, while malnutrition (low protein/albumin) impairs bone formation and increases sarcopenia and falls." (PMID 41009701, 2025). "Low albumin levels are typically indicative of chronic inflammation or malnutrition, and this condition may result in an imbalance in immune function, which in turn affects the clinical manifestations of asthma." (PMID 39980673, 2025). "Serum albumin is another important indicator of nutritional status, and a decrease in serum albumin level may indicate malnutrition or even cachexia." (PMID 41409247, 2025). "Low albumin levels usually suggest malnutrition or chronic wasting conditions, which may result in decreased soft tissue resilience and regenerative capacity." (PMID 40520340, 2025). "Elevated FAR values, often resulting from increased fibrinogen and/or decreased albumin, may indicate pronounced inflammation, hypercoagulability, or malnutrition, all of which contribute to poor clinical outcomes." (PMID 40607037, 2025). "Notably, the FT3/FT4 ratio demonstrated an independent association with nutritional status, as well as with transferrin and albumin levels, which are critical biomarkers of malnutrition and impaired hepatic function." (PMID 40725539, 2025). "After a complete assessment and laboratory tests identifying normocytic normochromic anemia and severe malnutrition (albumin 2.5) and one month of mixed nutrition, we performed revisional surgery with functional reversal of RYGB with later resolution of her nutritional deficiencies." (PMID 41556010, 2025). "These malnutrition markers (albumin, TC) can be commonly observed in patients with HF." (PMID 39673344, 2025). "Low albumin levels are frequently observed in chronic diseases and malnutrition." (PMID 40917661, 2025). "Interestingly, hemodialysis patients in our cohort demonstrated relatively preserved albumin levels despite lower BMI and the general expectation of higher malnutrition prevalence." (PMID 41295296, 2025). "It is important to note that many malnutrition risk assessment tools, such as the CONUT score, NRI score, and PNI score, are specifically designed for clinical contexts to assess malnutrition based on blood parameters like albumin, lymphocyte counts, and cholesterol." (PMID 41422111, 2025). "Both CRP and serum albumin (Alb) are useful markers for predicting morbidity and mortality in critically ill patients, as CRP is an effective marker of acute inflammation, whereas serum albumin (Alb) is an effective indicator of malnutrition status in critically ill patients." (PMID 40573094, 2025). "Therefore, low albumin levels are important in evaluating geriatric patients due to the presence of both malnutrition and increased inflammatory markers." (PMID 39838526, 2025). "In the past, serum albumin has been used as a marker for malnutrition." (PMID 40407919, 2025).